MYC (MYC proto-oncogene, bHLH transcription factor)
Diseases named in the same sentence as MYC in open-access papers (continued):
Sharing a sentence is not in itself a finding about the gene and the disease.
tumor (continued). "Recently, c-MYC was shown to regulate PD-L1 expression in mouse and human tumor cells, with suppression of c-MYC decreasing PD-L1 mRNA and protein levels." (PMID 30185888, 2018). "Calcium/PKCα-dependent activation of NUAK1 supports engagement of the AMPK-TORC1 metabolic checkpoint, thereby protecting tumour cells from MYC-driven cell death, and indeed, MYC selects for this pathway in part via transcriptional regulation of PKCα and ITPR." (PMID 29106388, 2018). "We demonstrate that GATAD2B enhances tumor growth, at least in part, through a direct interaction with MYC, a known potent oncogenic and metastasis driver that also scored in the in vivo screen." (PMID 30013058, 2018). "Clearly, these data indicate that the molecular mechanisms activating expression of MYC are different in cells derived from different tumours (see MUC1, MYC and MDSCs above)." (PMID 29784646, 2018). "miR-3140 downregulated the expression of BRD4-NUT fusion protein and MYC, and suppressed tumor cell growth in Ty-82 JQ1-R cells as well as Ty-82 cells." (PMID 29540837, 2018). "The evidence described here argues that diverse human tumor cell super-enhancers depend on the MYC CTCF site for optimal levels of enhancer-promoter looping and mRNA expression." (PMID 29641996, 2018). "Let-7 exerts its tumor suppressor function in part by inhibiting the expression of numerous oncogenes such as MYC, RAS, YAP1, HMGA2, and CDK6 and by altering cellular bioenergetics, including glucose metabolism." (PMID 30057901, 2018). "c-MYC depletion inhibits proliferation of human tumor cells at various stages of the cell cycle, being essential for sustaining proliferation." (PMID 30143666, 2018). "The response to MYCMI-6 correlates with MYC expression based on data from 60 human tumor cell lines and is abrogated by MYC depletion." (PMID 29968736, 2018). "We found that the simultaneous inhibition of AR and PDEF expression dramatically inhibited tumour growth and considerably reduced Ki67 and MYC expression." (PMID 30217192, 2018). "The combined results of cell-based and in vivo studies suggest that Vismodegib combined with BEZ235 exhibited sufficient anti-tumor activity against HH/MYC-driven MB at clinically achievable in vivo concentrations." (PMID 29682173, 2018). "To investigate the effects of tetrandrine on differentiation in vivo, we established a subcutaneous tumor xenograft model in athymic nude mice using the THP-1 cells overexpressing c-MYC or a control vector." (PMID 29700286, 2018). "Despite their inability to impact the proliferation or viability of FGFR3K644E plus MYC transformed MEFs, both tubastatin A and HDAC6 deficiency did significantly reduce tumor growth by these cells." (PMID 29423038, 2018). "MYC together with its heterodimerisation partner MAX functions as a tumour-promoting transcriptional regulator." (PMID 30217192, 2018). "CTCF binding is abrogated when its sequence motif is methylated, and the MYC enhancer-docking site occurs within a CpG island that is consistently hypomethylated in different tumor types as well as in different normal tissues." (PMID 29641996, 2018). "The tumour and normal colonic origins of the specimens is illustrated by higher levels of MYC in the tumour tissue." (PMID 29379130, 2018). "There is strong, uniform nuclear expression of MYC in all tumour cells and 100% proliferation by Ki67 immunostaining." (PMID 29518976, 2018). "We found that MAD1 over expression dramatically inhibited PDEF-mediated growth of and reduced PDEF overexpression-induced Ki67 and MYC expression in tumours isolated from the BC cell-inoculated nude mice." (PMID 30217192, 2018). "As a future aspect, it would be intriguing to investigate the expression of miR-17 and miR-200c in the surrounding stroma of the reported tumor types, and in particular for tumors with amplification or overexpression of the MYC oncogene family." (PMID 30473751, 2018).
tumor (continued). "This classification takes into account different molecular signatures of the primary tumor, such as MSI, hypermutator status, BRAF and KRAS mutations, WNT and MYC activation, TGF-β activation, and methylation status." (PMID 30282914, 2018). "Enrichment of pathways showed the interaction of these miRNAs with marked tumor suppression (PTEN, AXIN1, ATM, NLK), and important proto-oncogenes and tumor-promoting genes as MYC." (PMID 30201877, 2018). "Further, trametinib enhances the suppression of JQ1-induced MYC expression and tumor growth in colorectal cancer." (PMID 30459933, 2018). "Since 17-AAG was effective in suppressing MYC mRNA and protein expression while inhibiting tumor cell growth, we validated our results using another geldanamycin derivative, 17-dimethylaminoethylamino-17-demethoxy-geldanamycin (17-DMAG)." (PMID 30453475, 2018). "We showed that JQ1 decreased the binding of BRD4 to the MYC promoter to suppress MYC transcription, leading to decreased tumor cell proliferation." (PMID 30459933, 2018). "Let-7 exerts its tumor suppressor activity by regulating different oncogenes including MYC, RAS and CCND1." (PMID 30286096, 2018). "SIRT2 is also involved in tumour metabolism regulation through MYC stabilization by deacetylating H4K16ac." (PMID 30356832, 2018). "USP28 was the first FBW7-antagonizing DUB in an shRNA screen using c-MYC stability as a readout in human tumor cells." (PMID 29415985, 2018). "Tumor-bearing lung tissues from mice expressing EGFR or Kras oncogenes produce higher levels of Dusp6 RNA than do normal lung controls or tumor-bearing lungs from mice with a MYC transgene." (PMID 30475204, 2018). "A clearer understanding of the underlying mechanism of action of T‐025 inhibitor as a function of the tumor type, as well as the interplay between MYC and CLK2, is now needed." (PMID 29789342, 2018). "Overall, we established a key role of MYC as tumor reprogramming factor by guiding the acquisition of stem cell-like traits, thereby increasing the likelihood of neoplastic transformation upon further oncogenic insults." (PMID 29523784, 2018). "As Eμ‐MYC/Vav‐BFL1 DT mice can succumb to tumours as early as 29 days, we analysed the mice at 2 weeks of age in order to avoid transformed cells." (PMID 29498802, 2018). "MYC amplification was seen in an AFX sample of extraordinary tumor thickness of 17.5 mm (vs. median 3.25 mm for all samples)." (PMID 29765529, 2018). "The prevalence of potentially inactivating mutations as well as its ability to oppose MYC transforming activity, makes MGA a strong candidate for functioning as a tumor suppressor." (PMID 30054853, 2018). "MALDI-MS lipidomic analysis of the healthy and tumor lung tissue of high MYC activity mice revealed increasing signaling precursor phospholipids–phosphoinositides in tumor tissues while the surfactant lipids were predominant in healthy tissue." (PMID 28639235, 2017). "We also confirmed that the potent inhibitors of MEK and PI3K block tumor cell growth and MYC protein expression." (PMID 28152508, 2017). "Activated MYC signaling was also present in premalignant and tumor tissues from human lung SCC patients." (PMID 27935865, 2017). "MYC overexpression also contributes to maintaining the centroblast phenotype of BL tumour cells by promoting a GC-like gene expression programme." (PMID 28893938, 2017). "Conversely, inactivation of MYC by a tetracycline-inducible transgenic system resulted in tumor regression with decreased proliferation, differentiation, and apoptosis of tumor cells." (PMID 28607447, 2017). "This decrease in MYC mRNA occurred concomitantly with an increase in the levels of tumor-suppressive miRNAs such as members of the let-7 family and miR-34a-5p." (PMID 29163823, 2017).
tumor (continued). "Previous researches have demonstrated that c-MYC was essential for vasculogenesis and angiogenesis during development and tumor progression." (PMID 29088816, 2017). "The resulting mutant proteins act as dominant negatives of the FBXW7 protein resulting in increased expression of its protein targets, such as MYC to promote tumor growth." (PMID 28587062, 2017). "Overexpression of c-MYC is frequently observed in a wide variety of tumor types, and usually results from chromosome translocation involving the c-MYC genes in addition to gene amplification." (PMID 28740573, 2017). "By observing elevated expression of MYC, miR-19b-3p, miR-92a-3p and miR-92b-3p in eBL tumor cells compared to GC B-cells, we confirm that elevated expression of the miR-17~92 cluster miRNAs is a critical feature facilitating eBL lymphomagenesis." (PMID 29132323, 2017). "A more aggressive tumor phenotype is also found in double transgenic mice, c-MYC and E2F transcription factor 1 (E2F1)." (PMID 28422055, 2017). "CD4 helper cells were found to be critical to this effect, suggesting that MYC oncogenicity occurs not only through tumor-intrinsic mechanisms but also through host-dependent immune mechanisms." (PMID 29163537, 2017). "For example, MYC-driven tumor cells are highly dependent on ribosome biogenesis and protein synthesis, requiring a collaboration between MYC and mTOR signaling to satisfy the increased biosynthetic needs." (PMID 28443281, 2017). "Prior work has shown that a subset of pRCC, primarily Type 2 pRCC, is enriched for gene signatures of MYC activation and that tumours with MYC activation have a worse overall survival." (PMID 28593993, 2017). "Unlike signature A tumors, the signature B CNA patterns were quite distinct between tumor types, although some commonalities were observed including point mutations in oncogenes such as KRAS (LU and UCEC) and amplification of MYC (BRCA, LU, and OV)." (PMID 28202506, 2017). "Together, these observations suggest that oncogenes, such as MYC, establish and maintain tumor-cell specific DNA methylation patterns on a genome-wide level through modulating individual components of the DNA methylating machinery." (PMID 29100357, 2017). "On the basis of this performance, we applied the OT mini-classifier to the original OT-patient cohort, predicting that sensitive cases were mainly found in the ASCL2/MYC group, in particular early stage tumours (Fisher's exact test P=0.0068)." (PMID 28186126, 2017). "This indicates that HUWE1 suppresses intestinal tumourigenic at multiple levels, in part by stopping tumour initiation but (and consistent with the data on MYC above) also at the level of tumour growth." (PMID 28003334, 2017). "We first deconvolved from RGB into Hematoxylin (blue, cell nuclei), Permanent Red (pink, c-MYC) and DAB (brown, Cas3) a total 270 frames stained for c-MYC and Cas3 (10 fields/tumour sample)." (PMID 28974715, 2017). "In particular, MYC can induce EMT in driving tumor progression, but the reports demonstrate that this occurs post-transcriptionally." (PMID 29207623, 2017). "In transgenic animal models, overexpression of MYC leads to deregulated proliferation and tumor development in multiple tissues." (PMID 28583252, 2017). "PIM consistently phosphorylates and enhances OCT4 and MYC, which also contributes to the reprogramming of tumor cells." (PMID 28938604, 2017). "Apart from tumor cell-intrinsic effects, alterations in the immune surveillance can affect tumor maintenance and the response to MYC depletion." (PMID 28333115, 2017). "Acetylation of nucleosomal histones is a key mechanism through which MYC facilitates transactivation of genes important for tumor development and progression." (PMID 28505071, 2017). "Using in vivo model systems with conditional transgenic mice, inactivation of MYC consistently resulted in tumor regression in vivo in hematopoietic and solid tumors." (PMID 28590415, 2017).
tumor (continued). "The fact that those microRNAs have tumor-suppressive function in turn strengthens the notion that transrepression of genes is critical for MYC-dependent transformation." (PMID 28505071, 2017). "Entero/Goblets were mainly early stage tumours whereas ASCL2/MYC and ECM/EMT were rather late stages." (PMID 28186126, 2017). "FFPE sections of tumour identified a modal MYC signal pattern showing copy number gain (3-6 copies) in 69%, c-MYC amplification in 11% and diploid MYC signal in 20% of interphase cells analysed." (PMID 28460465, 2017). "Together, these MYC-induced metabolic alterations lead to rapid cell mass expansion and hence to tumor growth." (PMID 28333115, 2017). "In this regard, direct and indirect inhibition of c-MYC can be considered as a crucial function of miR-214 as a tumor suppressing regulator in NSCLC cells." (PMID 28076844, 2017). "Overexpression of LINC-ROR was able to increase tumor growth in xenograft experiments and was accompanied by an increase in MYC expression." (PMID 28704924, 2017). "Correspondingly, we reported that the inactivation of MYC in T-ALL causes changes in global histone H4 acetylation, H3K9me3 and H3K4me3 associated with cellular senescence and tumor regression." (PMID 29100357, 2017). "As we will discuss in more detail later, MYC inactivation results in tumor regression in most mouse models." (PMID 28333115, 2017). "Our data, however, suggest that even a reduction of CHK1 expression can be tumor suppressive, at least in the context of replication stress-driven tumors, modeled here by oncogenic MYC or irradiation damage." (PMID 29167438, 2017). "In growing tumours, an excess of dying cells is known to contribute to mass expansion, but the implication of MYC-mediated cell competition in this cancer trait has just begun to be investigated." (PMID 28420161, 2017). "Further analyses were performed in patients with low MYC transcript levels in tumor tissues compared with the corresponding ANCT by division into two subgroups based on the relative transcript level (>0.5 and <0.5)." (PMID 28480695, 2017). "An additional miRNA, miR-34a has been described as a tumor suppressor gene that downregulates MYC expression." (PMID 29163823, 2017). "Let-7 miRNA regulates the expression of several oncogenes, including RAS and MYC to inhibit cancer cell proliferation and tumor development." (PMID 28881790, 2017). "On the basis of this calculation, each tumour sample was attributed a c-MYC score, which was also in this case obtained by averaging the scores attributed to the ten frames analysed." (PMID 28974715, 2017). "The covariates used in the models were the patient’s age at surgery, pathological tumor stage, presence of lymph node invasion and interaction of the pRCC subtype (pRCC types 1 and 2) with the MYC staining patterns." (PMID 29180625, 2017). "This phenomenon suggests that potential epigenetic mechanisms are deployed by cells to compensate for the increase in c‐MYC copy number in this tumor." (PMID 28275007, 2017). "Given that MYC tumours resemble human papillary tumours histologically, while VM and VIM tumours resemble ccRCC, we wanted to determine if the similarities would also be apparent at the gene expression level." (PMID 28593993, 2017). "CDK1 inhibition induces MYC-dependent apoptosis in various tumor cells and the overexpression of MYC activates CDK2 and increases cyclin A/E gene expression." (PMID 28333115, 2017). "Transcriptome profiling of tumor samples has shown that several lncRNAs can be found differentially regulated by MYC in different cancer types and many of them can influence cancer cell viability and proliferation." (PMID 28704924, 2017). "With the aim to find a correlation between cell death in the stromal compartment and MYC overexpression in the tumour parenchyma, we proceeded with quantification of Caspase 3 and c-MYC signals." (PMID 28974715, 2017).
tumor (continued). "c-MYC modulates a wide range of fundamental biological processes and plays a pivotal role in tumor initiation and progression." (PMID 28076844, 2017). "Here, we report regarding the discovery of a novel therapy targeting the tumor microenvironment to overcome the poor prognosis of intractable DLBCL with MYC rearrangement." (PMID 28055963, 2017). "Diclofenac, a non-steroidal anti-inflammatory drug, has recently shown the ability to inhibit GLUT-1, LDH-A, and MCT1 expression in cancer cell lines, along with decreased MYC activity, resulting in reduced cell proliferation and tumor growth." (PMID 28362357, 2017). "In summary, we conclude that DNMT3B contributes to tumor maintenance of MYC-driven T-ALL cells through its effects on DNA methylation, and that loss of DNMT3B causes the reactivation of gene transcription through reversing promoter/CpG island methylation." (PMID 29100357, 2017). "By controlling transcription of GCN5, MYC exerts broad effects on global chromatin structure establishing a tumor-cell specific pattern." (PMID 29100357, 2017). "Conversely, inhibition of c‐MYC expression is thought to be also an essential mechanism by which BET inhibitors suppress tumor progression in hematological malignancies." (PMID 28275007, 2017). "Similar results were observed for AML4-ALK, BRAF and DDR2 mutant or MYC amplified tumours in The Cancer Genome Atlas (TCGA) data set." (PMID 28220783, 2017). "Of the DE miRNAs, there was a marked number targeting critical tumor suppressors (PTEN, AXIN1, ATM, NLK) and critical proto-oncogenes and tumor promoting genes such as MYC." (PMID 29132323, 2017). "The BET-bromodomain inhibitor OTX015 (MK-8628) has potent antiproliferative activity accompanied by c-MYC down-regulation in several tumor types, and has demonstrated synergism with the mTOR inhibitor everolimus in different models." (PMID 27935867, 2017). "To define a specific MYC signature that can be used to classify tumor subtypes, we selected a total of 16 genes." (PMID 28275007, 2017). "Inhibition of MYC results in mitochondrial dysfunction, and a resulting accumulation of lipid droplets in tumor cells." (PMID 28362357, 2017). "The switchable nature of MYC in these transgenic tumor models allowed for analysis of the dynamics in chromatin structure and associated gene expression patterns." (PMID 28505071, 2017). "We successfully identified the drug, emetine, which was effective against intractable DLBCL with MYC rearrangement, through the use of a high-throughput drug screening system using primary patient tumor cells." (PMID 28055963, 2017). "Other studies have evaluated the activity of MCT1 inhibitors in SCLC, an alternate tumor setting where frequent MYC amplifications are observed." (PMID 29050199, 2017). "In another study, the analysis of the excessive Wnt/β-catenin and c-MYC signaling pathways was performed in a large number of human tumor specimens and biopsies from 85 patients." (PMID 28422055, 2017). "Since GSK3β induces phosphorylation and degradation of its downstream targets, and some GSK3β substrates are key proteins for promoting cell survival, such as β-Catenin, Cyclin D1, eIF2B and MYC, it was initially considered as a tumor suppressor." (PMID 28800359, 2017). "For example, co-expression of c-MYC and transforming growth factor-alpha (TGFα) as transgenes in the mouse liver resulted in a dramatic acceleration of neoplasia as compared with the expression of either of these transgenes alone." (PMID 28422055, 2017).